THPO (thrombopoietin)
Diseases named in the same sentence as THPO in open-access papers (continued):
Sharing a sentence is not in itself a finding about the gene and the disease.
Thrombocytopenia (continued). "Thrombocytopenia in cirrhosis arises from splenic sequestration, increased platelet destruction, reduced thrombopoietin production, and ethanol-induced toxic effects on platelets." (PMID 39518754, 2024). "Thrombocytopenia was ultimately successfully managed using recombinant human thrombopoietin, prednisone, and recombinant human interleukin-11." (PMID 38903494, 2024). "Studies have shown that VLBW neonates exhibit a limited ability to respond to thrombocytopenia, both in platelet production and in thrombopoietin secretion." (PMID 39852436, 2024). "Thrombocytopenia, frequently attributed to heightened platelet sequestration in the spleen and diminished thrombopoietin production, is a prevalent characteristic of cirrhosis, substantially impacting platelet counts and function." (PMID 39184703, 2024). "An increase in serum thrombopoietin due to thrombocytopenia stimulates the megakaryocytes in the bone marrow and raises the number of platelets in the blood." (PMID 37593313, 2023). "Initial strategies designed to treat thrombocytopenia via manipulation of the thrombopoietin signalling pathway involved recombinant human thrombopoietin." (PMID 37568597, 2023). "Cirrhotic patients with thrombocytopenia have been treated with thrombopoietin (TPO) receptor agonists such as lusutrombopag a few weeks before invasive procedures, markedly reducing the need for platelet transfusion." (PMID 37231349, 2023). "Thrombocytopenia was more frequently encountered in HR-SF, most likely due to decreased thrombopoietin levels in advanced liver disease and direct bone marrow suppression." (PMID 38069218, 2023). "While this study did not allow the authors to establish a causal link between the presence of anti-TPO antibodies and a reduced platelet count, a prior report did suggest the direct impact of anti-THPO antibodies on thrombocytopenia." (PMID 38005902, 2023). "In terms of drugs, first-generation recombinant thrombopoietin initially showed promise in reducing chemotherapy-related thrombocytopenia in early clinical trials." (PMID 38041150, 2023). "Eltrombopag is a thrombopoietin-mimetic, but it improves not only thrombocytopenia but also cytopenias of other series." (PMID 37790070, 2023). "Thrombocytopenia, a common complication of liver cirrhosis, is mainly due to decreased synthesis of thrombopoietin in the liver and increased breakdown of platelets in the spleen." (PMID 37720512, 2023). "Gene variants of THPO and MPL cause THPO-related thrombocytopenia and congenital amegakaryocytic thrombocytopenia (CAMT), respectively." (PMID 36534659, 2022). "The aim of this study was to evaluate the comparative therapeutic value of recombinant human thrombopoietin (rhTPO) in treating sepsis patients with thrombocytopenia." (PMID 36683598, 2022). "Thrombocytopenia is secondary to hypersplenism, possible immune-mediated mechanisms, direct viral suppression of platelet production, and reduced production of thrombopoietin." (PMID 35801214, 2022). "Eltrombopag had been used previously to support patients with HCV infection, cirrhosis, and thrombocytopenia with successful results, as such patients have liver function impairment with a reduced level of thrombopoietin." (PMID 35626194, 2022). "Thrombocytopenia is related to chronic liver disease due to the impaired production of platelets and the decreased hepatic synthesis of thrombopoietin; therefore, PLR can vary depending on liver function, but also on systemic inflammation." (PMID 36553125, 2022). "Two newly licensed oral thrombopoietin mimetics/receptor agonists, avatrombopag and lusutrombopag, are now available for targeted treatment of thrombocytopenia in patients with advanced liver disease, who are undergoing invasive procedures." (PMID 33917431, 2021).
Thrombocytopenia (continued). "In parallel to more severe thrombocytopenia in Vivaxhigh patients, plasma levels of cytokines inducing megakaryocytic differentiation in the BM, thrombopoietin (TPO), and IL-11 were significantly increased in this cluster." (PMID 34585667, 2021). "The reason behind significant thrombocytopenia in advanced fibrosis is decreased production of the glycoprotein hormone thrombopoietin by the damaged liver." (PMID 34646672, 2021). "Thrombocytopenia was also evident in these sequentially infected mice, consistent with a decrease in circulating levels of thrombopoietin." (PMID 34286101, 2021). "The increased platelet clearance, along with increased platelet consumption, lung damage, dysfunctional bone marrow microenvironment, decreased thrombopoietin production, and antiviral drug use is the possible vital factor for thrombocytopenia COVID-19 cases." (PMID 35113977, 2021). "Thrombocytopenia, which is frequently observed in patients with CLD and cirrhosis, can manifest due to a decreased thrombopoietin production and accelerated platelet destruction caused by hypersplenism." (PMID 34829846, 2021). "This real-world, observational study aimed to assess and compare the clinical efficacy and safety of eltrombopag with recombinant human thrombopoietin (rhTPO) in the treatment of chemotherapy induced thrombocytopenia (CIT) in patients with lymphoma." (PMID 34490101, 2021). "Thrombocytopenia in liver disease results from increased splenic sequestration due to portal hypertension and subsequent hypersplenism, decreased thrombopoietin (TPO) production, and/or from toxic or virus-induced suppression of megakaryocytopoiesis." (PMID 33917431, 2021). "The observation of thrombocytopenia and increased thrombopoietin, while counterintuitive, is reflective of the current literature, and the precise underlying mechanism remains to be elucidated in both COVID-19 and other viral infections." (PMID 34336889, 2021). "On the other side, biological behavior plays the decisive role in prognosis of advanced-stage HCC, HCC patients with thrombocytopenia which reflected less thrombopoietin and IL-6 induced by less malignant tumor would have a better prognosis." (PMID 33573630, 2021). "Given that thrombocytopenia is frequently seen in liver failure, due to splenic sequestration as a result of portal hypertension and decreased thrombopoietin synthesis, liver cell necrosis appears to be one of the driving factors of ferritin change." (PMID 34252125, 2021). "Other factors such as low serum levels of thrombopoietin, translocated toxins or other gut-derived substances, anti-platelet antibodies also play important roles in thrombocytopenia." (PMID 33573590, 2021). "Before implantation, recombinant human thrombopoietin (rh-TPO) was usually given to the patients with thrombocytopenia until the peripheral platelet count reached beyond 50 × 109/L." (PMID 32158688, 2020). "In clinical practice, recombinant human THPO (rhTHPO) had been used for patients with severe thrombocytopenia." (PMID 32260359, 2020). "The presence of anti-THPO antibody relates to thrombocytopenia and is rarely seen in hematopoietic and autoimmune diseases." (PMID 32260359, 2020). "RESCUE trial is aim to explore the effect of a platelet-elevating drug, recombinant human thrombopoietin (rhTPO), as an effective rescue therapy on sepsis patients with acute severe thrombocytopenia." (PMID 31492102, 2019). "The cases described in this paper and in the previous studies all have reduced serum levels of THPO, whereas ordinarily THPO levels should be elevated in cases of aplastic anemia or other forms of thrombocytopenia." (PMID 29191946, 2018). "Thrombocytopenia also an abnormality revealed by CBC which related to the reduction of thrombopoietin formation by the liver along with elevated utilization of thrombocytes." (PMID 29915506, 2018).
Thrombocytopenia (continued). "Thrombocytopenia is strongly related to the degree of liver fibrosis owing to low thrombopoietin levels and splenic sequestration of blood cells as a direct result of elevated portal pressure, especially among patients with advance fibrosis or cirrhosis." (PMID 30155312, 2018). "The oral thrombopoietin (TPO) receptor agonist lusutrombopag (Mulpleta®) was developed to improve thrombocytopenia in patients with chronic liver disease prior to elective invasive medical procedures." (PMID 32025904, 2018). "Thrombocytopenia is related to chronic liver disease due to impaired platelet production and decreased hepatic synthesis of thrombopoietin." (PMID 29370777, 2018). "Severe thrombocytopenia is accompanied by a raise in plasma thrombopoietin (TPO) levels, when the megakaryocyte-platelet mass is reduced, and it is known that excess TPO has a direct effect on hematopoietic stem cells." (PMID 27152938, 2016). "Patients with liver cirrhosis also typically have thrombocytopenia due to the accumulation and destruction of platelets in the spleen and due to the reduced synthesis of thrombopoietin." (PMID 27518399, 2016). "The incidence of thrombocytopenia was higher in healthy volunteers than in immune compromised cancer patients, and similar to our study, also the antibodies against THPO disappeared over time." (PMID 27617228, 2016). "The liver is the largest single site of thrombopoietin production, producing the hormone in both constitutive and inducible fashion, a finding that helps to explain the thrombocytopenia seen in patients with hepatic failure." (PMID 27766065, 2016). "Thrombocytopenia in dengue correlated with high thrombopoietin level which stimulated platelet recovery." (PMID 27015272, 2016). "An established total of 708 patients with sepsis and thrombocytopenia will undergo prospective random assignment to recombinant human thrombopoietin or placebo (a 1:1 ratio)." (PMID 25986785, 2015). "It is well established that following initial thrombocytopenia due to consumption, thrombocyte counts increase after trauma in response to release of thrombopoietin." (PMID 26607226, 2015). "The aim of this study was to evaluate serum thrombopoietin levels and its relationship with thrombocytopenia at patients with cirrhosis." (PMID 24976834, 2014). "The mechanism of thrombocytopenia is thought as splenic sequestration and destruction of platelets, impaired bone marrow generation and diminished hepatic thrombopoietin synthesis." (PMID 24976834, 2014). "The aim of this study was to evaluate serum thrombopoietin levels and its relationship with thrombocytopenia inpatients with cirrhosis." (PMID 24976834, 2014). "The mechanism of thrombocytopenia is thought as splenic sequestration and destruction of platelets, impaired bone marrow generation and diminished hepatic thrombopoietin (TPO); principal regulator of megakaryo-thrombopoiesis; production." (PMID 24976834, 2014). "The most common adverse events were dose-dependent anemia and thrombocytopenia, which were anticipated because thrombopoietin and erythropoietin signal through JAK2." (PMID 24283202, 2013). "The most commonly observed adverse events (AEs) in the phase III trials were dose-dependent anemia and thrombocytopenia, which were anticipated as thrombopoietin and erythropoietin signal through JAK2." (PMID 24283202, 2013). "Thrombopoietin treatments can reduce thrombocytopenia, megakaryocytic suppression, and the quick onset of lethality in LT-challenged mice." (PMID 23555687, 2013). "Research has focused on developing compounds specifically to stimulate thrombopoietin (TPO) activity in order to prevent or treat thrombocytopenia in chronic liver diseases." (PMID 21415958, 2009).
Thrombocytopenia (continued). "Since thrombocytopenia is often very difficult to correct with platelet administration only, due to splenic sequestration and short platelet survival, thrombopoietin agonists are a good alternative, although their effect requires time for proper correction (approximately 10 days)." (PMID 41597390, 2026). "The main mechanisms responsible for thrombocytopenia in chronic liver disease are increased platelet destruction, splenic sequestration, and reduced hepatic synthesis of thrombopoietin (TPO), a key hormone that regulates megakaryocyte proliferation and platelet production." (PMID 41597390, 2026). "Theoretically, conditions that are distinguished by isolated thrombocytopenia can be caused by other reasons as well, such as poor platelet production due to relative or absolute lack of thrombopoietin." (PMID 40722539, 2025). "The question of thrombocytopenia is also of particular importance because selinexor inhibits thrombopoietin signaling and thereby may be toxic to early megakaryopoiesis." (PMID 40001478, 2025). "The increased levels of THPO may reflect compensatory hematopoietic responses to thrombocytopenia, a common hematologic manifestation in GD that results from Gaucher cell infiltration of the bone marrow." (PMID 40671914, 2025). "In patients with cirrhosis, thrombocytopenia may be due to reduced thrombopoietin in addition to distributional thrombocytopenia." (PMID 39857914, 2025). "One of the mechanisms through which the coagulation pathway is affected is that patients with cirrhosis have variable degrees of thrombocytopenia, which is due to increased platelet destruction, increased splenic and hepatic sequestration, and decreased levels of thrombopoietin." (PMID 39997034, 2025). "Thrombocytopenia mechanisms include portal hypertension-induced platelet sequestration in the spleen, potential myelodysplasia suppression, immune-related platelet destruction, and diminished thrombopoietin production, primarily synthesized by the liver." (PMID 40018344, 2025). "Conversely, activators could address thrombocytopenia by modulating the ASGR1-Notch1-thrombopoietin axis." (PMID 40429734, 2025). "Thrombocytopenia may result from liver failure, which impairs thrombopoietin production, a hormone essential for platelet generation." (PMID 40666600, 2025). "Although thrombopoietin agonists and targeted medicines are non-invasive alternatives for treating cirrhosis-related thrombocytopenia, clinical trials are being conducted to see if they may improve thrombocytopenia in cirrhotic patients." (PMID 39859975, 2024). "Thrombocytopenia treatment with interleukin 11 and thrombopoietin was successfully completed." (PMID 39507704, 2024). "Thrombocytopenia in patients with Chronic Liver Disease is explained by portal hypertension leading to pooling of platelets in an enlarged spleen or reduced hepatic production of thrombopoietin." (PMID 39092367, 2024). "Thrombocytopenia resulting from destruction of megakaryocytes and megakaryocyte precursors, rather than platelet destruction, may be attenuated by recombinant human thrombopoietin administration." (PMID 39618596, 2024). "A thrombopoietin-mimetic oral drug eltrombopag has been successfully used for the treatment of immune thrombocytopenic purpura, aplastic anemia, and some myelodysplastic syndrome-related thrombocytopenias." (PMID 37790070, 2023). "The aim of this study was to determine whether thrombocytopenia in human SGA infants is due to insufficient thrombopoietin (TPO) production." (PMID 35568734, 2023). "Additional mechanisms for observed thrombocytopenia may involve reduced hepatic production of thrombopoietin in NAFLD." (PMID 37108182, 2023). "This longitudinal, case-control study aimed to investigate the role of thrombopoietin (TPO) and anti-TPO antibodies in HIV-associated thrombocytopenia, focusing on the changes seen before and after the initiation of highly active antiretroviral therapy (HAART)." (PMID 38005902, 2023).
Thrombocytopenia (continued). "THPO-related thrombocytopenia in the proband was revealed using multitarget panel NGS sequencing." (PMID 36534659, 2022). "Antibodies cross-reacting with thrombopoietin may induce thrombocytopenia, a condition observed in COVID-19 patients." (PMID 35891400, 2022). "The assay for IPF is a non-invasive method of assessing platelet turnover or thrombopoiesis in different types of thrombocytopenia, a simple predictor of bone marrow recovery after transplantation, or used to monitor the response to therapy with growth factors such as thrombopoietin." (PMID 35740728, 2022). "Thrombocytopenia is also a sequela of medical diseases such as chronic liver disease due to decreased production of thrombopoietin and splenic sequestration in the setting of portal hypertension, and also in acute liver failure although the mechanism is less understood." (PMID 34618180, 2022). "Whilst treatment-related thrombocytopenia is a well-established adverse effect of Panobinostat, in this setting of progressive disease it is likely that plasma cell infiltration in bone marrow further contributes to thrombocytopenia by triggering thrombopoietin (TPO) production." (PMID 35797277, 2022). "Thrombocytopenia and increased MPV levels in HCC patients may result from decreased activity of thrombopoietin and bone marrow suppression associated with chronic hepatitis C virus (HCV) or hepatitis B virus (HBV) infection and antiviral therapy application." (PMID 35668355, 2022). "Decreased thrombopoietin production in the liver and increased platelet sequestration in the spleen followed by liver cirrhosis and hypersplenism were the major mechanisms of thrombocytopenia." (PMID 33573630, 2021). "Furthermore, when we see patients with low platelets and no findings of suggesting nonalcoholic steatohepatitis (NASH) or cirrhosis, the possibility of anti-THPO antibody needs to be considered, in addition to drug-related thrombocytopenia or ITP." (PMID 32260359, 2020). "Unexplained mild thrombocytopenia in patients with T2DM might be due to an overlooked presence of the anti-THPO antibody." (PMID 32260359, 2020). "They concluded that thrombocytopenia on admission mostly resulted from platelet consumption, and that thrombopoiesis might respond to increased thrombopoietin." (PMID 29381746, 2018). "Finally, another heterozygous THPO R31* was observed but this time in two families of inherited thrombocytopenia." (PMID 28955303, 2017). "Mild to moderate thrombocytopenia after transplantation can be observed due to many factors, such as reduced hepatic thrombopoietin production, allograft sequestration, hypersplenism, haemorrhage, heparin-induced thrombocytopenia, immunologic reactions, hemolysis, drugs, infections, and sepsis." (PMID 28328941, 2017). "TPO regulates nearly all stages of the megakaryocyte (MK) differentiation, and this explains that numerous diseases characterized by an alteration in MK/platelet production leading to thrombocytopenia or thrombocytosis are due to either acquired or hereditary mutations in MPL, THPO, or JAK2." (PMID 28955303, 2017). "The serum thrombopoietin level of ITP in pregnancy (1283 ± 646 pg/mL) was significantly higher than gestational thrombocytopenia (187 ± 64 pg/mL) (P < 0.01), although the platelet counts of these two disorders may overlap." (PMID 26840092, 2016). "Given the role of thrombopoietin in stimulating proliferation and differentiation of megakaryocytes, our previous study investigated the potential benefits of recombinant human thrombopoietin in severe sepsis patients with thrombocytopenia." (PMID 25986785, 2015). "In some healthy volunteers who received this agent, neutralizing antibody against PEG-rhMGDF was detected and these antibodies neutralized its activity but also cross-reacted with and neutralized endogenous thrombopoietin to produce a paradoxical thrombocytopenia." (PMID 26527459, 2015).